LYZL2 (lysozyme like 2)
Synonyms: LYZD2
Tractability: Antibody: UniProt places it where antibodies can reach, with high confidence; UniProt predicts a signal peptide or a membrane-spanning region; its Gene Ontology location is reachable by antibodies, with medium confidence.
Gene: Protein-coding gene on chromosome 10 (30,611,779 to 30,629,762, reverse strand). Ensembl gene ENSG00000151033.
Subcellular location: Secreted
Gene Ontology:
Molecular function: lysozyme activity
Cellular component: extracellular region
Genetic constraint (gnomAD): Loss-of-function variants: 13 observed, 17.21 expected, observed/expected ratio (o/e) 0.76, 90% interval 0.49 to 1.2. The upper end of that interval is the gene's LOEUF score, 1.2, which puts it in group 5 of 6, group 1 being the genes least tolerant of losing a copy. Missense variants: 163 observed, 180.41 expected, observed/expected ratio (o/e) 0.9, 90% interval 0.8 to 1.03. Synonymous variants: 63 observed, 69.51 expected, observed/expected ratio (o/e) 0.91, 90% interval 0.74 to 1.12.
Homologues: Orthologues: chimpanzee LYZL2 (97% identical), mouse Lyzl1 (74% identical), rat Lyzl1 (68% identical), rabbit LYZD1 (61% identical), zebrafish lyz (45% identical), Drosophila melanogaster LysD (35% identical), Drosophila melanogaster LysB (34% identical), Drosophila melanogaster CG11159 (34% identical), Drosophila melanogaster CG30062 (34% identical), Drosophila melanogaster LysE (34% identical), Drosophila melanogaster LysS (34% identical), Drosophila melanogaster LysP (33% identical), and 4 more. Paralogues in human: LYZL1 (97% identical), LYZ (45% identical), SPACA5 (44% identical), SPACA5B (44% identical), SPACA3 (42% identical), LYZL4 (39% identical), LYZL6 (38% identical), LALBA (33% identical).
Diseases named in the same sentence as LYZL2 in open-access papers:
LYZL2 is named in the same sentence as 10 diseases in open-access papers, as found by Europe PMC text mining. Sharing a sentence is not in itself a finding about the gene and the disease. The quoted sentences say what the papers report.
dental caries (1 paper, 2014). The decay of a tooth, in which it becomes softened, discolored, and/or porous. "Dental caries’ GWAS identified significant signals in LYZL2, AJAp1, and KPNA4; and efforts are ongoing to identify genetic factors for multiple caries phenotypes." (PMID 24702466, 2014).
LYZL2 also shares sentences with these, for which no sentence is quoted: infection (3 papers); bacterial infection (1); breast carcinoma (1); Hyperglycemia (1); male infertility (1); neurological disorders (1); Obesity (1); psoriasis (1); tumor (1).